TRPM7 (transient receptor potential cation channel subfamily M member 7)
Diseases named in the same sentence as TRPM7 in open-access papers (continued):
Sharing a sentence is not in itself a finding about the gene and the disease.
brain ischemia (11 papers, 2010 to 2025). Diminished or absent blood supply to the brain caused by obstruction (thrombosis or embolism) of an artery resulting in neurologic damage. "Knockdown of TRPM7 in isolated cortical neurons or in the hippocampus delayed neuronal death caused by oxygen glucose deprivation and brain ischemia, respectively." (PMID 20567598, 2010). "Carvacrol, a phenolic monoterpene and putative TRPM7 inhibitor, has demonstrated neuroprotective activity in cerebral ischemia models." (PMID 41357867, 2025). "Since TRPM7 is a putative target of miRNA135a, the aim of the present paper was to evaluate the role played by miRNA135a in cerebral ischemia." (PMID 37718696, 2024). "The present paper showed that icv administration of miR135a ameliorates brain ischemia and improves general and focal neurological deficits by mediating an early reduction in TRPM7 levels in the cortex." (PMID 37718696, 2024). "All these findings strongly support the fundamental role of TRPM7 during cerebral ischemia and the medical need of tools able to suppress its activation in order to achieve neuroprotection." (PMID 37718696, 2024). "Following exposure to brain ischemia, we found that deleting TRPM7 reduced the infarct volume in both lines of transgenic mice." (PMID 35406741, 2022). "To achieve our aim, we generated two lines of conditional knockout mice, with deletion of TRPM7 in PV neurons and in CaMKII neurons and subjected them to brain ischemia followed by behavioral, histological, cellular and biochemical analyses." (PMID 35406741, 2022). "Several lines of research demonstrate a relationship between Akt signaling pathway and the neuroprotective effects of TRPM7 suppression during brain ischemia." (PMID 35406741, 2022). "Suppression of TRPM7 following brain ischemia reduces neuronal death, infarct volume and motor disability." (PMID 35406741, 2022). "Suppression of TRPM7 in hippocampus CA1 neurons facilitates neuron survival after brain ischemia, and preserves neuronal morphology and function." (PMID 25799367, 2015). "Previous studies indicated that TRPM7 is highly expressed in the brain and plays a critical role in anoxic neuronal death by mediating Ca2+ influx during the cerebral ischemia and prolonged oxygen-glucose deprivation (OGD)." (PMID 25799367, 2015). "Interestingly, our experiments showed that administration of the mimic ameliorates brain ischemia and improves both general and focal neurological deficits by mediating an early reduction in TRPM7 protein levels in the cortex." (PMID 37718696, 2024). "The early prevention of TRPM7 activation is protective during brain ischemia." (PMID 37718696, 2024). "Collectively, the results of the present work showed for the first time that the miR135a administration may pave the way for an innovative therapeutic intervention based on an early prevention of TRPM7 activation during brain ischemia." (PMID 37718696, 2024). "Thus, our data support the link between TRPM7 suppression and activation of Akt under brain ischemia pathologies, but clearly indicate that such activation is dependent on the cell type in which TRPM7 was deleted (i.e., cell-type-specific mechanism)." (PMID 35406741, 2022). "Thus, we concluded that both GABAergic PV and glutamatergic neurons are protected by the deletion of TRPM7 in GABAergic PV neurons, but only glutamatergic neurons are protected by the deletion of TRPM7 in glutamatergic neurons after brain ischemia." (PMID 35406741, 2022). "Oxidative stress induced by brain ischemia upregulates transient receptor potential melastatin-like-7 (TRPM7) expression and currents, which could contribute to neurotoxicity and cell death." (PMID 35406741, 2022). "Furthermore, brain ischemia increased TRPM7 expression in PV neurons more than that in CaMKII neurons." (PMID 35406741, 2022). "TRPM7 has several electrophysiological characteristics that might be clues for identifying a solution to damage arising from cerebral ischemia." (PMID 30486272, 2018).
brain ischemia (continued). "The present study was conducted to determine whether carvacrol, a TRPM7 inhibitor, has neuroprotective effects with regard to global cerebral ischemia-induced hippocampal neuronal death." (PMID 30486272, 2018). "The proinflammatory cytokine IL-6 contributes to regulation of Ca2+ influx in cerebral ischemia, but the role of IL-6 in regulating TRPM7 functioning is unknown." (PMID 27010689, 2016). "Suppression of Trpm7 makes neurons resistant to ischemic death following brain ischemia." (PMID 27375434, 2016). "Both IL-6 and TRPM7 are up-regulated in cerebral ischemia and are known to contribute to neuronal damage, but it is unknown whether these two molecules interact during this process." (PMID 27010689, 2016). "As knockdown of the TRPM7 channel reduces the pathogenesis of brain ischemia, it is tempting to speculate that 5-LOX inhibitors achieve a portion of their cellular protective effects by blocking the TRPM7 channel." (PMID 20567598, 2010). "Thus, brain ischemia resulted in upregulation of TRPM7 in PV and CaMKII neurons." (PMID 35406741, 2022). "Indeed, it has been shown that suppression of hippocampal TRPM7 by intrahippocampal injections of viral vectors bearing shRNA specific for TRPM7 makes neurons resistant to ischemic death after brain ischemia and preserves neuronal morphology and function in rats." (PMID 22934072, 2012). "Recently, Sun and colleagues demonstrated that suppression of TRPM7 channels in vivo by a virally mediated gene silencing through shRNA reduced the death of hippocampal CA1 pyramidal neurons and preserved functions after global cerebral ischemia." (PMID 37718696, 2024).
colorectal cancer (11 papers, 2017 to 2025). A primary or metastatic malignant neoplasm that affects the colon or rectum. "We wondered whether hypomagnesemia would prove protective in the development of colorectal cancer, and whether this could be linked to TRPM7 activity." (PMID 28810912, 2017). "The Personalized Prevention of Colorectal Cancer Trial is a double-blind, precision-based randomized controlled trial with 240 participants randomly assigned to both treatment and TRPM7 genotype." (PMID 40946805, 2025). "An analysis of a public genomic database and patient data from a Chinese medical center revealed that expression of TRPM7 positively correlated with tumor infiltration, lymph node metastasis, distant metastasis and the clinical stage of colorectal cancer." (PMID 38255793, 2024). "The suppression of TRPM7 function reduced the cell proliferation, migration and invasion of colorectal cancer cells in vitro, by modulating EMT." (PMID 38255793, 2024). "Materials and Methods: In this study, we aimed to analyze clinical and prognostic characteristics of TRPM7 expression in colorectal cancers (CRC) using The Cancer Genome Atlas." (PMID 36363540, 2022). "Survival analysis was performed to expose the prognostic value of TRPM7 in colorectal cancer." (PMID 36363540, 2022). "TRPM7 reportedly plays a role in human inflammatory bowel disease (IBD) and colorectal cancer, but the role of TRPM7 in the pathogenesis of NEC remains vague." (PMID 36159330, 2022). "In addition, a recent study showed that TRPM7 was involved in the pathophysiology of human inflammatory bowel disease (IBD) and colorectal cancer." (PMID 36159330, 2022). "Importantly, it has been reported that TRPM7 was overexpressed in human inflammatory bowel disease (IBD) and colorectal cancer." (PMID 36159330, 2022).
cervical cancer (10 papers, 2019 to 2024). A primary or metastatic malignant neoplasm involving the cervix. "Progesterone has been shown to reduce TRPM7 expression in human cervical cancer cells reducing cell proliferation and switching from necrosis to apoptosis." (PMID 38255793, 2024). "Cervical cancer cell proliferation, invasion and migration were suppressed by miR-543 in vitro and tumor growth in vivo in part targeting TRPM7." (PMID 38255793, 2024). "In cervical cancer, TRPM7 expression regulated miR-543-mediated cell cycle arrest, increased apoptosis in vitro, and inhibited tumor growth in vivo." (PMID 38784033, 2024). "PI3K/Akt and p38/MAPK pathways have been suggested to be involved in miR-543/TRPM7-regulated cervical cancer development." (PMID 38255793, 2024). "Both miRNAs, miR-543 and miR-192-5p, directly target TRPM7, inhibiting tumor growth, migration and invasion driven by this channel in cervical cancer." (PMID 37762011, 2023). "TRPM7 is also found to be aberrantly overexpressed and/or activated in cervical cancer, and has been discovered as the direct therapeutic target for cervical cancer." (PMID 36230965, 2022). "Restoration of TRPM7 expression partially reversed the tumor suppressive role of miR-543 on cervical cancer progression by promoting cell proliferation and invasion and attenuating cell apoptosis." (PMID 36230965, 2022). "For instance, miR-543/TRPM7 axis participates in cervical cancer progression through PI3K/Akt and p38/MARK pathways." (PMID 34409031, 2021). "On balance, the progesterone treatment turns the acid‐induced volume change from NVI to AVD and cell death from apoptosis to necrosis by suppressing TRPM7 expression in the human cervical cancer cells." (PMID 31293101, 2019). "In human cervical cancer HeLa cells, here, for the first time, we demonstrated that progesterone reduces the endogenous expression of TRPM7 molecule and its channel activity as well as the cell proliferation." (PMID 31293101, 2019). "Furthermore, tumor suppressor miR-192-5p inhibited cervical cancer cell proliferation and invasion by targeting TRPM7." (PMID 38255793, 2024). "In addition, we studied the impact of TRPM7 KO on human HeLa cells, which were derived from cervical cancer." (PMID 39513908, 2024). "In cervical cancer cells, TRPM7 mediates necrotic cell death dependent on acidic pH." (PMID 37762011, 2023). "However, after progesterone treatment, TRPM7 expression and activity are inhibited, preventing cervical cancer cell growth and switching cell death from acidotoxic necrosis to apoptosis." (PMID 37762011, 2023). "There are two microRNAs (miRNAs) able to downregulate TRPM7 in cervical cancer." (PMID 37762011, 2023). "In addition, hsa-miR-543 can target TRPM7 to inhibit cervical cancer." (PMID 34475953, 2021). "In this study, TRPM7 channel activity was, for the first time, demonstrated to play an essential role in the acidotoxic induction of NVI and necrotic cell death in human cervical cancer HeLa cells." (PMID 31293101, 2019). "In this study, therefore, a possible involvement of TRPM7 in acidotoxic NVI and necrotic death in human cervical cancer HeLa cells was first investigated, not only because the normal vaginal pH is strongly acidic but also because TRPM7 is known to be aberrantly expressed in malignant tumor cells." (PMID 31293101, 2019).
melanoma (10 papers, 2013 to 2025). A malignant, usually aggressive tumor composed of atypical, neoplastic melanocytes. "TRPM7 is frequently overexpressed in melanoma cells and is linked to enhanced proliferation, migration, and epithelial–mesenchymal transition (EMT)." (PMID 40869148, 2025). "Malignant melanoma has been shown to contain mutated TRPM7 that possesses oncogenic properties." (PMID 37445615, 2023). "In addition, TRPM7 expression levels have been shown to be associated with an invasive behavior and metastatic potential in cutaneous melanoma cell line and is also expected to act as a protector in both melanocyte physiology and in melanoma cells." (PMID 35053440, 2022). "TRPM1 has been implicated in tumor suppression, while TRPM7, TRPV1, and TRPV4 have been observed to function as both melanoma suppressors and oncogenic drivers, modulating proliferation, apoptosis and metastasis." (PMID 40869148, 2025). "Experimental silencing of TRPM7 has been shown to impair melanoma cell motility and reduce metastatic potential, highlighting its functional relevance." (PMID 40869148, 2025). "TRPM1 is implicated as a tumor suppressor, whereas TRPM7, TRPV1, and TRPV4 often function as both melanoma suppressor or oncogenic drivers, modulating proliferation, apoptosis, and metastasis." (PMID 40869148, 2025). "In melanoma, TRPM7 has been reported to be overexpressed in melanoma cell lines, but its function is not completely known in these cells." (PMID 37445615, 2023). "In contrast, TRPM7 has a protective and detoxifying function in melanoma cells, and it is highly expressed in metastatic melanoma." (PMID 26336993, 2015). "The pharmacological inhibition of TRPM7 using compounds such as waixenicin A or NS8593 has been shown to exert anti-proliferative and anti-metastatic effects not only in melanoma but also in other malignancies, underlining its potential as a broad-spectrum therapeutic target." (PMID 40869148, 2025). "The expression of TRPM7 was reported in melanocytes and in cell lines derived from melanoma." (PMID 38255793, 2024). "In summary, studies have shown several novel roles for TRPM7 in cancer, collectively establishing foundations for further research that may potentially benefit future melanoma patients via identifying, screening, preventing, and creating a prognosis." (PMID 37445615, 2023). "Interestingly, a recent study using transcriptomic profiling of canine cancers identified TRPM7 as a biomarker of melanoma and SPPL2A as a highly relevant target." (PMID 35053440, 2022). "Among the oncogenic TRP isoforms, TRPM7, TRPV1, TRPV4, and TRPM8 have received considerable attention due to their frequent overexpression in melanoma cells and their functional contributions to the malignant phenotype." (PMID 40869148, 2025). "This review highlights the physiological expression of key TRP subfamilies (TRPM1, TRPM7, TRPM8, TRPV1, TRPV4, and TRPM2) in melanocytes and discusses their dysregulation in melanoma cells." (PMID 40869148, 2025). "Plateau phases in melanoma cells are produced by STIM1/ORAI1 store-operated Ca2+ entry and mechanosensitive TRPM7/TRPV4 channels, which transform perivascular forces and osmotic conditions into electrical signals." (PMID 41463339, 2025). "Brain extracellular ion concentrations (Ca2+, K+, glutamate) also drive patterned electrical activity in melanoma cells via ORAI1-STIM1 store-operated entry and TRPM7/TRPV4 mechanosensitive channels." (PMID 41463339, 2025). "Altered expression patterns and functional changes in TRPM1, TRPM7, TRPM8, TRPV1, and TRPV4 have notably been found to modulate cell survival, apoptosis, proliferation, and migration in melanoma models." (PMID 40869148, 2025). "In the context of melanoma, several TRP channel subtypes, including TRPM1, TRPM7, TRPV1, and TRPV4, have been shown to be differentially expressed and functionally active in tumor cells." (PMID 40869148, 2025).
melanoma (continued). "As previously discussed, other members of the TRPM subfamily (TRPM1, TRPM5, TRPM7, and TRPM8) appear to have essential roles in melanoma." (PMID 37445615, 2023). "A recent study revealed that TRPM7 was involved in the proliferation of canine and human non-UV-induced melanomas." (PMID 38255793, 2024). "TRPM7 thus appears to be an important gene for non-UV-induced melanomas, as it was recently found to be (i) involved in several other human cancers; (ii) significantly mutated in human oral melanomas; and (iii) involved in intrachromosomal translocation in acral melanoma in a previous study." (PMID 35053440, 2022). "In the present study, we showed that TRPM7, SPPL2A, and GABPB1 are involved in the proliferation of canine and human non-UV-induced melanomas." (PMID 35053440, 2022).
pancreatic adenocarcinoma (10 papers, 2012 to 2025). "The high expression of CNNM4 is also correlated with high expression of TRPM7 and MAGT1, another magnesium transporter, and this TRPM7/MAGT1/CNNM4 signature is associated with low patient survival in pancreatic adenocarcinoma." (PMID 41395111, 2025). "While the mechanism underlying the aberrant overexpression of TRPM7 in malignant neoplasia has yet to be determined, the existing data support the exploration of its clinical significance in pancreatic adenocarcinoma and the other malignancies." (PMID 24278689, 2012). "The variable levels of TRPM7 expression in pancreatic adenocarcinoma may be related to the underlying tumor heterogeneity." (PMID 25770184, 2015). "Moreover, small interfering RNA mediated silencing of TRPM7 induced senescence-associated β-galactosidase in pancreatic adenocarcinoma cells, suggesting a novel role of ion channels in replicative senescence of cancer." (PMID 25079291, 2014). "Besides pancreatic adenocarcinoma, the role of TRPM7 has also been implicated in cancers that arise in other organs, such as retinoblastoma, head and neck carcinoma, gastric carcinoma, breast carcinoma, and nasopharyngeal carcinoma." (PMID 24278689, 2012). "It is reported that TRPM7 is overexpressed in human pulmonary carcinoma and pancreatic adenocarcinoma." (PMID 34938330, 2021). "This pattern was also observed in the pancreas wherein TRPM7 was expressed in apical plasma membrane of pancreatic ductal epithelia and in the cytoplasm of pancreatic adenocarcinoma cells." (PMID 33617107, 2021). "In studies using human pancreatic adenocarcinoma cell lines, TRPM7 channels have been shown to be necessary for maintaining proliferation and preventing replicative senescence." (PMID 28379203, 2017). "The expression levels of TRPM7 in pancreatic adenocarcinoma tissues were found to positively correlate with the primary tumor size and tumor stages." (PMID 28379203, 2017). "Studies have demonstrated increased expression of TRPM7 in a panel of human pancreatic adenocarcinoma cells and tissues." (PMID 28379203, 2017). "In pancreatic adenocarcinoma, TRPM7 is required for Mg2+-dependent cell migration and cell invasion." (PMID 28379203, 2017). "In pancreatic adenocarcinoma, a positive correlation was identified between the aberrant over-expression of TRPM7 and the tumor size/stages." (PMID 28379203, 2017). "Anti-TRPM7 immunoreactivity was examined in pancreatic adenocarcinoma, adenosquamous carcinoma, solid pseudopapillary neoplasm, acinar cell carcinoma, and neuroendocrine tumor." (PMID 25770184, 2015). "In human pancreatic adenocarcinoma cells in which TRPM7 is highly expressed, short hairpin RNA-mediated suppression of TRPM7 impairs cell invasion." (PMID 25770184, 2015). "We have translated the embryological and genetic studies of exocrine pancreas organogenesis in zebrafish into identification of the TRPM7 ion channels in human pancreatic adenocarcinoma." (PMID 25770184, 2015). "In this study, we determined the expression levels of TRPM7 in pancreatic tissue microarrays and correlated these measurements in pancreatic adenocarcinoma with the clinicopathological features." (PMID 25770184, 2015). "To determine the clinical significance of TRPM7 in pancreatic adenocarcinoma, we further analyzed the expression of TRPM7 in detail and correlated it with the clinical and pathological features." (PMID 25770184, 2015). "The majority of the pancreatic adenocarcinoma specimens (66%) exhibit moderate to high anti-TRPM7 immunoreactivity." (PMID 25770184, 2015). "On the basis of the percent coverage by IHC separated by staining intensity and tumor stages, the expression levels of TRPM7 in pancreatic adenocarcinoma are displayed." (PMID 25770184, 2015). "In culture studies using human pancreatic adenocarcinoma cell lines, TRPM7 channels have been shown to be necessary for maintaining proliferation and preventing replicative senescence." (PMID 25770184, 2015).